ZFP36L2 (ZFP36 like 2 zinc finger CCCH-type)
Diseases named in the same sentence as ZFP36L2 in open-access papers (continued):
Sharing a sentence is not in itself a finding about the gene and the disease.
asthma (2 papers, 2021 to 2023). "The tristetraprolin (TTP) family of RBPs, consisting of ZFP36, ZFP36L1 and ZFP36L2 in humans, has been implicated in the regulation of immune responses, but little is known about their role in epithelium or asthma." (PMID 37928904, 2023). "Restoring ZFP36L1 and ZFP36L2 levels in primary bronchial epithelial cells from patients with severe asthma led to decreased expression of mRNAs encoding pro-inflammatory factors." (PMID 37928904, 2023). "While this may infer an increase in their nuclear role, our integration of Zfp36l2 targets showed that ZFP36L2 exerts its effects mainly by modulating polyribosome association of mRNAs in severe asthma." (PMID 37928904, 2023). "In summary, our analysis inferred that ZFP36L1 and ZFP36L2 encoding mRNAs are present in distinct airway epithelial cells and that ZFP36L2 preferentially targets mRNAs that are bound to polyribosomes in bronchial epithelial cells from patients with severe asthma." (PMID 37928904, 2023). "We observed significantly decreased binding of ZFP36L1 and ZFP36L2 mRNAs to polyribosomes in primary bronchial epithelial cells from severe asthma patients compared to age- and sex-matched healthy controls (both p < 0.05)." (PMID 37928904, 2023). "Taken together, our data show that ZFP36L1 and ZFP36L2 are expressed in airway epithelial cells and that their levels and subcellular localization are modified in asthma, in a severity-dependent manner." (PMID 37928904, 2023). "ZFP36L1 and ZFP36L2 alter post-transcriptional gene expression in bronchial epithelial cells in severe asthma, granting further investigation into their role in chronic airway inflammation." (PMID 37928904, 2023). "Restoring the levels of ZFP36L1 and ZFP36L2 in primary bronchial epithelial cells from patients with severe asthma decreased the mRNA expression of IL6, IL8 and CSF2." (PMID 37928904, 2023). "Our data demonstrate that ZFP36L1 and ZFP36L2 levels and subcellular localization are dysregulated in primary samples from both human and murine-like asthma." (PMID 37928904, 2023). "Together, our data strongly suggest that ZFP36L1 and ZFP36L2 drive changes in gene expression in primary epithelial cells in asthma." (PMID 37928904, 2023). "We assessed the lung mRNA expression and cellular localization of Zfp36l1 and Zfp36l2 in precision cut lung slices in murine asthma models." (PMID 37928904, 2023). "In bronchial biopsies, we observed a trend towards increased nuclear localization for ZFP36L2 in patients with severe asthma while ZFP36L1 appeared more localised in the cytosol." (PMID 37928904, 2023). "To determine the effects of restoring ZFP36L1 and ZFP36L2 levels, we employed a vector to overexpress Zfp36l1 and siRNAs to deplete ZFP36L2 in primary bronchial epithelial cells from patients with severe asthma." (PMID 37928904, 2023). "We further explored the potential role of ZFP36L1 and ZFP36L2 in bronchial epithelial cells in asthma." (PMID 37928904, 2023). "We also found decreased of Zfp36l1 and Zfp36l2 mRNA in chronic asthma-like inflammation (akin to human severe asthma) in mice." (PMID 37928904, 2023). "Immunostaining of human bronchial biopsies showed that airway epithelial cell staining of ZFP36L1 was decreased in severe asthma as compared with mild, while ZFP36L2 was upregulated." (PMID 37928904, 2023). "Modulating ZFP36L1 and ZFP36L2 in primary bronchial epithelial cells from patients with asthma decreased the expression of known pro-inflammatory mediators." (PMID 37928904, 2023). "Contrary to mRNA expression, ZFP36L2 protein appeared upregulated in patients with severe asthma, i.e., on high doses of inhaled and/or oral glucocorticoids." (PMID 37928904, 2023). "We have also performed in silico analysis of publicly available datasets of Zfp36l2 targets and observed that these are particularly enriched in genes that present increased binding to polyribosomes in severe asthma human primary bronchial epithelium." (PMID 37928904, 2023).
asthma (continued). "ZFP36L1 and ZFP36L2 mRNAs appeared differentially expressed in individual airway epithelial cell types, with these expression patterns varying between health and asthma." (PMID 37928904, 2023). "have reported that ZFP36L2 expression in peripheral blood CD4+ T cells is significantly higher in severe asthma patients than in mild asthma patients." (PMID 34276705, 2021). "Together, these data point towards chronic inflammation driving changes in ZFP36L1 expression in asthma, while glucocorticoids may be the main drivers of ZFP36L2 protein expression in severe asthma." (PMID 37928904, 2023). "Finally, we determined the expression in airway epithelium of ZFP36L1 and ZFP36L2 in human bronchial biopsies and performed rescue experiments in primary bronchial epithelium from patients with severe asthma." (PMID 37928904, 2023). "After having analysed the levels of ZFP36L1 and ZFP36L2 in omics mRNA datasets and inferring their role in ARE regulation and epithelial cell biology, we interrogated their expression levels in an in vivo model of asthma." (PMID 37928904, 2023). "To further investigate the dysregulation of both ZFP36L1 and ZFP36L2 mRNA levels in human and mouse asthma we performed immunostaining of ZFP36L1 and ZFP36L2 in bronchial biopsies from patients with different asthma severities and non-asthma controls." (PMID 37928904, 2023).
autoimmune disease (2 papers, 2020 to 2022). A disorder resulting from loss of function or tissue destruction of an organ or multiple organs, arising from humoral or cellular immune responses of the individual to their own tissue constituents. "Although further studies are needed, selective fine-tuning of ZFP36L2 affecting Helios expression in iTregs could be an effective strategy for the treatment of autoimmune diseases." (PMID 32655569, 2020). "In addition, ZFP36L2 is involved in the process of hematopoietic stem cell differentiation and thymogenesis and may be related to the development of human autoimmune diseases." (PMID 35928229, 2022). "Thus, with the goal of better understanding the mechanistic role of ZFP36L2 in autoimmune diseases, we set up experiments to study the expression of ZFP36L2 in CD4+ T cells and find novel ZFP36L2-target mRNAs that could modulate regulatory T cells (Tregs)." (PMID 32655569, 2020). "Collectively, these findings suggest that ZFP36L2 is involved in the physiopathology of autoimmune diseases in humans; however, the precise role of ZFP36L2 in a specific T cell population has not been elucidated." (PMID 32655569, 2020).
cleft lip (2 papers, 2022 to 2024). Congenital defect in the upper lip where the maxillary prominence fails to merge with the merged medial nasal prominences. "Interestingly, recent studies found that ZFP36L2 was significantly associated with nsCL/P and one of its subtypes, i.e., non-syndromic cleft lip only, in GWAS data from a Chinese Han population." (PMID 39489835, 2024).
COVID-19 (2 papers, 2022 to 2025). A disease caused by infection with severe acute respiratory syndrome coronavirus 2. "In their study, IFI44L in B cells, S100A8 in monocytes, and NCR2 in natural killer cells were identified as crucial markers that are involved in the innate immune response of COVID-19, while it was also demonstrated that ZFP36L2 in CD4+ T cells can regulate the inflammatory process of COVID-19." (PMID 40163554, 2025). "Other features such as ZFP36L2 in CD4+ T cells can regulate the inflammatory process of COVID-19." (PMID 35928229, 2022).
hypothyroidism (2 papers, 2016 to 2021). Abnormally low levels of thyroid hormone. "Therefore, the hypothyroidism detected in the Zfp36l2-/- females might be a causative factor in several of the phenotypes associated with ZFP36L2 activity loss." (PMID 34502288, 2021). "In our previous work, we observed that levels of the mRNA of ZFP36L2, a protein that can promote RNA degradation, were increased during thyroid development and reduced during hypothyroidism promoted by environmental stressors, as well as during thyroid carcinogenesis." (PMID 34502288, 2021). "In our previous work, we suggested that the ZFP36L2 reduction promoted by environmental factors might contribute to the observed pancytopenia by promoting hypothyroidism." (PMID 34502288, 2021). "Collectively, the data show evidence of hypothyroidism in the t-Zfp36l2-/- females and that the inactivation of Zfp36l2 in the thyroid affects the function of the gland in more ways than its development and morphology, except for the slight increase in apoptosis detected in the t-Zfp36l2-/- females." (PMID 34502288, 2021). "Furthermore, our data provide candidate molecular mechanisms (deregulated expression of Bcl2, Zfp36l2, Egr1 and Hmga1) for the pesticides-induced hypothyroidism." (PMID 27905518, 2016). "Furthermore, the detected hypothyroidism might also contribute to ZFP36L2′s influence on ovulation and oocyte maturation." (PMID 34502288, 2021).
lung adenocarcinoma (2 papers, 2023 to 2025). A carcinoma that arises from the lung and is characterized by the presence of malignant glandular epithelial cells. "In another study, LINC00173 was shown to be down-regulated pattern in lung adenocarcinoma (LUAD), which significantly contribute to down-regulate ZFP36L2 expression while the activity of miR-1275 towards the target expression was not hindered by LINC00173." (PMID 40251826, 2025).
multiple sclerosis (2 papers, 2020 to 2022). A progressive autoimmune disorder affecting the central nervous system resulting in demyelination. "Also, ZFP36L2 was found to be a disease-susceptibility gene in multiple sclerosis (MS), and decreased ZFP36L2 expression was observed in MS patients as compared with healthy controls." (PMID 32655569, 2020). "The expression level of ZFP36L2 in patients with multiple sclerosis (MS) was reduced compared with healthy controls." (PMID 35928229, 2022).
prostate carcinoma (2 papers, 2014 to 2022). A carcinoma that arises from epithelial cells of the prostate gland. "By inspection, we also identified at least 10 additional transcription factors within 500 kb of 9 other GWAS loci, that are also reasonable candidates for contributing to prostate cancer risk: SOX13, ZFP36L2, ATOH8, DLX1 & DLX2 (same locus), GATA2, SKIL, SP8, ASCL2, and DPF1." (PMID 24497837, 2014).
psoriasis (2 papers, 2022 to 2023). An autoimmune condition characterized by red, well-delineated plaques with silvery scales that are usually on the extensor surfaces and scalp. "Other psoriasis-related genes also enriched in the most ZFP36L2-deficient cells included the effector chemokine CXCL1315 (ρ = −0.49, p < 5.9 × 10−320)." (PMID 35977472, 2022). "We investigate this regulatory pattern primarily in our Trm1 subpopulation, in which Th17/Tc17 cytokines are expressed in psoriasis samples and can be studied directly, but other inflammatory markers negatively correlate with ZFP36L2-deficiency in other T cell classes." (PMID 35977472, 2022). "Plotting ZIST program member expression against ZFP36L2 levels in Trms/Th17/Tc17 cells from these pre- and mid-treatment psoriasis lesions shows that despite resolution of visible inflammatory plaques, the overall inflammatory-suppressive gradient in T cells remains sharply suppressed." (PMID 35977472, 2022). "Additional shared signatures between ILCs and T cells were related to genes that regulate tissue residency (FOS and NR4A1; module 18) as well as quiescence (TSC22D3, DUSP1, ZFP36L2, and KLF6; module 22), the latter recently shown to be expressed by plastic skin ILCs in a mouse model of psoriasis." (PMID 37160121, 2023).
T-cell leukemia (2 papers, 2014 to 2018). A malignant disease of the T-lymphocytes in the bone marrow, thymus, and/or blood. "Furthermore, it was also reported that deletion of murine Zfp36l1 and Zfp36l2 leads to perturbed thymic development and T-cell leukemia." (PMID 29449217, 2018).
bladder cancers (1 paper, 2021). "The frequency of ZFP36 gene family mutations ranged between 9.1 and 10%, among the three bladder carcinoma cohorts; notably, mutations of ZFP36L1 and ZFP36L2 were mutually co-occurring (P = 0.02; FDR = 0.06)." (PMID 33397444, 2021). "When we combined mutations of ZFP36L2 and ZFP36 to ZFP36L1, the frequency of ZFP36 gene family mutations reached 3% (n = 297) in all TCGA cohorts, with the highest frequencies observed in bladder cancers." (PMID 33397444, 2021).
brain cancer (1 paper, 2021). A primary or metastatic malignant neoplasm affecting the brain. "Therefore, we verified the relationship between the regulators and above‐mentioned autophagy‐related genes by knockdown and overexpression ZFP36L2 and RAB13 in Human Brain Cancer Cell Lines SW1088 cells." (PMID 34632655, 2021).
Cachexia (1 paper, 2022). Severe weight loss, wasting of muscle, loss of appetite, and general debility related to a chronic disease. "In addition, consistent with higher percentage of effector-memory CD8+ T cells in non-cachexia patients, genes relevant to the dysfunctional phenotype and the state of inactivation such as MT1X, MT1E, IL7R, and ZFP36L2 were highly expressed in CD8+ T cells in non-cachexia patients." (PMID 36376273, 2022).
cardiomyopathy (1 paper, 2022). A disease of the heart muscle or myocardium proper. "mTORc1 is activated in murine pregnancy, and rapamycin treatment reverses the cardiomyopathy associated with Zfp36l2 deletion." (PMID 35316214, 2022). "To determine whether the postpartum cardiomyopathy associated with Zfp36l2 deletion is due to its specific effects on the mTORc1 pathway and its hyperactivation, we treated female pregnant mice with 1 mg/kg subcutaneous rapamycin every other day in the third trimester of the first pregnancy." (PMID 35316214, 2022). "Because constitutive activation of mTORc1 leads to cardiomyopathy, it is not surprising that Zfp36l2 deletion leads to a similar phenotype in pregnancy." (PMID 35316214, 2022). "Collectively, these results indicate that the effects of Zfp36l2 deletion on cardiac function are specific to PPCM and not other forms of cardiomyopathy." (PMID 35316214, 2022).
chronic asthma (1 paper, 2023). An asthma that is characterized by the development of persistent airway inflammation and recurrent attacks of breathlessness and wheezing, which vary in severity and frequency. "Mechanistically, it possible that expression levels of ZFP36L1 and ZFP36L2 are driven by different mechanisms in, particularly, severe/chronic asthma." (PMID 37928904, 2023).
colitis (1 paper, 2020). Inflammation of the colon. "We finally examined the function of ZFP36L2 iTregs in vivo by using a T cell transfer model of colitis." (PMID 32655569, 2020). "We also found that the forced expression of ZFP36L2 decreased the suppression function of Tregs in the in vitro suppression assay as well as in the adoptive transfer model of colitis." (PMID 32655569, 2020). "Indeed, the suppression of IFN-γ production by ZFP36L2 may partly influence the results of the colitis model because IFN-γ is well-known to be involved in the induction of colitis." (PMID 32655569, 2020). "Interestingly, ZFP36L2-expressing iTregs have reduced suppression property on the proliferation of naïve CD4+ T cells in vitro as well as the development of the T cell transfer model of colitis." (PMID 32655569, 2020). "In this experiment, ZFP36L2 iTregs or mock iTregs were adoptively co-injected with naive CD4+ T cells into RAG2−/− mice, and the development of colitis was evaluated by histological analyses and by its effect on the mice weight." (PMID 32655569, 2020). "However, when ZFP36L2 iTregs were co-injected, no significant improvement was observed on histological evaluation of the colitis nor the body weight, suggesting that ZFP36L2 iTregs have limited suppression function in vivo." (PMID 32655569, 2020).
colorectal tumor (1 paper, 2020). "Additionally, we found a heterozygous nonsense mutation in APC and frameshift indels in known colorectal tumor suppressors; ATM, SOX9, RNF43, and ZFP36L2, of likely driver status." (PMID 32697969, 2020).
endometriosis (1 paper, 2017). The growth of functional endometrial tissue in anatomic sites outside the uterine body. "In order to examine if HuR/TTP axis contributes to the pathophysiology of endometriosis, we evaluated expression of Zfp36, Zfp36l1, Zfp36l2 and Elavl1 in eutopic and ectopic lesions obtained from syngeneic BALB/cByJ mouse model of endometriosis." (PMID 28724967, 2017).
Flavivirus Infections (1 paper, 2025). Infections with viruses of the genus FLAVIVIRUS, family FLAVIVIRIDAE. "The present study clarified the role of human ZFP36L2 in the defense response of the host against flavivirus infection." (PMID 39972499, 2025). "Overall, this study unveiled the crucial antiviral role of human ZFP36L2 during flavivirus infection, thus shedding light on the distinct antiviral mechanisms employed by proteins of the ZFP36-like family." (PMID 39972499, 2025). "ZFP36L2 inhibited flavivirus infection solely through the 5′-3′ XRN1 RNA decay pathway, whereas ZFP36L1 inhibited JEV infection via the 5′-3′ XRN1 and 3′-5′ RNA exosome RNA decay pathways." (PMID 39972499, 2025). "In contrast with the antiviral mechanism of ZFP36L1 against flaviviruses in which ZFP36L1 recruits both the 5′-3′ XRN1 and 3′-5′ RNA exosome pathways to degrade flavivirus RNA, ZFP36L2 impedes flavivirus infection through a 5′-3′ XRN1-mediated RNA decay pathway." (PMID 39972499, 2025). "In the present study, we identified ZFP36L2 as another member of the zinc finger 36-like protein family, which also played a role in the defense of the host against flavivirus infection, thereby expanding our understanding of the biological role of this molecule in host antiviral defense." (PMID 39972499, 2025). "Therefore, the ZFP36L1 and ZFP36L2 proteins may serve a dual purpose during flavivirus infection by defending against the virus and downregulating the host’s inflammatory response, to maintain a balance between the control of viral replication and the prevention of excessive inflammation." (PMID 39972499, 2025). "ZFP36L2 restricts flavivirus infection by approximately tenfold through XRN1-mediated antiviral activity, suggesting that this pathway may partially, but not completely, accounts for ZFP36L2’s antiviral effect." (PMID 39972499, 2025).
glioblastoma (1 paper, 2024). The most malignant astrocytic tumor (WHO grade IV). "Our results align with the findings obtained from glioblastoma research, that is, inhibiting ZFP36L2 expression can promote tumor apoptosis." (PMID 39767767, 2024).